TRPC6 (transient receptor potential cation channel subfamily C member 6)
Diseases named in the same sentence as TRPC6 in open-access papers (continued):
Sharing a sentence is not in itself a finding about the gene and the disease.
kidney diseases (continued). "Targeting TRPC6 using pharmacological or genetic interventions could ameliorate podocyte injury and delay the progression of kidney diseases." (PMID 36257404, 2022). "The relationship between TRPC6 and nephropathy has been extensively investigated." (PMID 31998809, 2020). "The cell type specific regulation of glomerular function by TRPC6 may provide a clue for intentionally manipulating the channel function in a specific cell type to treat kidney disease based on renal phenotypes." (PMID 28646178, 2017). "TRPC6 was down-regulated at both the mRNA and protein levels after inhibition of the mTORC2 signaling pathway in our study, providing a potential therapeutic target for kidney diseases." (PMID 25393730, 2014). "Therefore, maintaining TRPC6 expression and function at normal levels is a primary goal for the treatment of kidney diseases." (PMID 25393730, 2014). "The mutant TRPC6 may affect the functions of this complex, leading to abnormalities in podocyte foot processes of many renal diseases." (PMID 22701654, 2012). "On the basis of previous findings, the TRPC6 expression level and channel function may contribute to the pathogenesis of kidney disease via a dysregulated Ca2+ influx." (PMID 22701654, 2012). "Perhaps, blocking the TRPC6 channel may be candidate for diagnosis and therapeutic target of renal diseases." (PMID 22545060, 2012). "All these findings revealed a novel annotation of TRPC6 during the development of the CNS and kidney, which provided a new handhold for us to understand the development of hippocampus and kidney, as well as the mechanism of learning or memory and kidney diseases in the future." (PMID 22701654, 2012). "Considering their prominent role in lung and kidney diseases, TRPC5 and TRPC6 have emerged as the most promising therapeutic targets." (PMID 41118703, 2025). "In subsequent sections, we will describe changes in TRPC6 that have been observed in human diseases and in animal disease models, and we will then review studies that test the hypothesis that knockout or inactivation of TRPC6 will slow the progression of kidney disease." (PMID 36421724, 2022). "Although TRPC5 and TRPC6 have received the most attention, accumulating evidence suggests that TRPC3 also plays a role in kidney diseases." (PMID 31877991, 2019). "Therefore, further pre‐clinical and clinical studies are now invited to uncover whether the targeted manipulation of activities of certain PKC isoforms might be beneficial in the therapeutic management of given proteinuric kidney diseases with altered TRPC6 functions." (PMID 26404773, 2015). "The rapid onset and progression of renal disease in the index patient is not typical of TRPC6-FSGS renal pathology, nor are the histological findings on renal biopsy." (PMID 37615749, 2023). "Mild histological and biochemical manifestations of kidney disease are found primarily in the tubulointerstitial compartment as a result of albumin overload, and these do not appear to be ameliorated by TRPC6 inactivation." (PMID 35805070, 2022). "The canonical transient receptor potential channel 6 (TRPC6), a type of non-selective Ca2+ channel, is involved in many renal diseases." (PMID 34307458, 2021). "The canonical transient receptor potential channel 6 (TRPC6), a nonselective cation channel that allows passage of Ca2+, plays an important role in renal disease." (PMID 30282964, 2018). "Despite this strong evidence relating TRPC6 with different forms of kidney diseases, and the recent availability of specific drugs to modulate the TRPC6 activity, there is a lack of targeted treatments for Trpc6 related kidney diseases." (PMID 34012910, 2015). "To investigate the function of TRPC6 in podocytes and its relation to proteinuria in kidney diseases, we over-expressed TRPC6 in podocytes by puromycin aminonucleoside (PAN) and observed the changes of foot processes, TRPC6 protein distribution, and mRNA expression." (PMID 22545060, 2012).
kidney diseases (continued). "However, mice and rats in which TRPC6 is knocked out or completely inactivated show no signs of kidney dysfunction and are at least partially protected in several kidney disease models." (PMID 41165237, 2025). "Transient receptor potential cation channel 6 (TRPC6) is a nonselective cation channel, and abnormal expression and gain of function of TRPC6 are involved in the pathogenesis of hereditary and nonhereditary forms of renal disease." (PMID 25393730, 2014). "However, protective effects of pharmacological TRPC5 inhibition have not been seen by all investigators, and the over-expression of either wild-type or dominant-negative TRPC5 channels in glomeruli does not appear to induce kidney disease, in contrast to what is seen with over-expression of TRPC6." (PMID 35805070, 2022). "This review highlights the data implicating TRPC6 and other TRPC family members in both genetic and non-genetic forms of kidney disease, focusing on TRPC3, TRPC5, and TRPC6 in a cell type (glomerular podocytes) that plays a key role in proteinuric kidney diseases." (PMID 31877991, 2019).
cancer (50 papers, 2008 to 2025). A tumor composed of atypical neoplastic, often pleomorphic cells that invade other tissues. "There is a possibility that there are contraindications to the use of positive TRPC6 modulators in patients at risk of the onset and progression of cancer." (PMID 34948414, 2021). "Literature data indicate that TRPC6 is associated with tumorigenesis, tumor growth and elevated TRPC6 expression was detected in many cancer types." (PMID 32765303, 2020). "As our results indicate that TRPC6 knockdown significantly attenuates relevant features of cancer cells, such as proliferation, migration and in vitro invasion, we have explored the possible mechanism underlying the functional role of TRPC6 in these cells." (PMID 30223530, 2018). "Among TRP, TRPC6 is to date the only one being implicated in GBM angiogenesis suggesting that specific TRPC6 inhibitors could simultaneously target both cancer progression and vascularization, thereby improving the efficacy of standard (radio-chemotherapy) options." (PMID 33928077, 2021). "Genetic variants in TRPC6 have been associated with the development of doxorubicin-induced cardiotoxicity, suggesting that TRPC6 may be a therapeutic target for cardioprotection in cancer patients." (PMID 35096991, 2021). "TRPC3 and TRPC6 have been implicated in DOX-mediated cardiotoxicity, whereas TRPC5 has been associated with P-glycoprotein-induced chemoresistance in cancer cells." (PMID 39594815, 2024). "Inhibition of TRPC6 activity by pharmacological agents can suppress the proliferation of cancer cells." (PMID 38567350, 2024). "Growing evidence has reported that the pattern of the expression of TRPC6 proteins is upregulated in several pathophysiological conditions, including cancer." (PMID 37892239, 2023). "In summary, we demonstrated that Trpc6 deficiency alone is sufficient to protect male mice from doxorubicin-induced cardiac damage and decline in cardiac function, suggesting that TRPC6 may be a valuable therapeutic target for cancer patients who require doxorubicin." (PMID 35096991, 2021). "Hypoxia can be sensed by several TRP channels such as TRPM7 and TRPA1, TRPC1, TRPC6, both in cancer cells and in stromal cells." (PMID 29772843, 2018). "In conclusion, the present study provides strong evidence at the molecular level for supporting the clinical trials focused on the use of TRPC6 blockers in cancer therapy." (PMID 28030826, 2017). "Recent studies indicate that the transient receptor potential canonical 6 (TRPC6) channel is highly expressed in several types of cancer cells." (PMID 28030826, 2017). "Therefore, activated TRPC6 may be a unique hallmark in malignant cells, and according to the TRPC6 knockout mouse model, targeting of TRPC6 should not affect normal cell function and thus is feasible for treatment of cancers." (PMID 28030826, 2017). "The TRP canonical 6 (TRPC6) channel is highly expressed in several types of cancer cells including NSCLC cells." (PMID 28030826, 2017). "Since ROS is involved in both cancer progression and its regulation, thus it is important to identify the role of TRPC6 protein in the cancer disease development or regulation." (PMID 23976973, 2013). "The results showed that quenching of the intracellular calcium release via TMB-8 abolished TRPC6-mediated apoptosis in cancer cells." (PMID 23976973, 2013). "Over-expression of TRPC6 results in calcium-dependent apoptotic death and activation of apoptotic genes in a variety of cancer cells." (PMID 23976973, 2013).
cancer (continued). "The cellular factors like membrane receptor activation via TFN-α and cellular Ca2+ store depletion involved in cancer progression have been known to induce TRPC6 expression." (PMID 23976973, 2013). "In the present study, we report that TRPC6 (11q22) is overexpressed in HNSCC, and provide new evidence that increase in gene dosage is a novel mechanism to activate TRPC6 expression in cancer." (PMID 23497198, 2013). "The physiological and cellular factors involved in cancer disease progression are also known to regulate the cellular TRPC6 expression." (PMID 23976973, 2013). "Taken together, these data suggest that TRPC6 inhibition may serve as a potential cardioprotective therapy for male and post-menopausal female cancer patients that require doxorubicin." (PMID 35096991, 2021). "In addition, TRPC6-dependent signaling pathways are involved in the development of various types of cancers, as well as in the dysfunction of cells of the immune system." (PMID 34948414, 2021). "Previously induction of TRPC6 was reported to promote the aggressive phenotype of various cancer cells by promoting a sustained elevation of intracellular Ca2+ level, which is critical for cancer cells proliferation and migration." (PMID 33916304, 2021). "Specifically, Orai1 and TRPC6 channels are well established to be implicated in cell proliferation and migration and various hypertrophic gene expression is reported to be mediated by NFAT pathway activation in normal and cancer cells." (PMID 33916304, 2021). "TRPC6 involvement in cancer is based on its Ca2+ permeability." (PMID 32887220, 2020). "In vitro knockdown of TRPC6 decreased proliferation and migration in these cancer cells." (PMID 32138386, 2020). "Inhibition of TRPC6 by low pH of the tumor environment could be an advantageous factor, considering that this channel is also highly expressed in cancer-infiltrating immune cells (see Section 5.1) and in stromal cells such as pancreatic stellate cells." (PMID 32887220, 2020). "In addition to TRPC1 and TRPC3, the involvement of TRPC6 in cancer cell invasion and migration has been extensively investigated." (PMID 32138386, 2020).
cancer (continued). "Since the expression of TRPC6 calcium channel was high, we asked if TRPC6 might be involved in the increase in the cellular calcium levels in GaQ3-treated cancer cells." (PMID 23976973, 2013). "Over-expression of TRPC6 results in significant apoptosis in cancer cells." (PMID 23976973, 2013). "Moreover, aberrant TRPC6 expression has been observed in cancer, and TRPC6 might be involved in tumor progression and metastasis." (PMID 41373637, 2025). "WNKs are important kinases that can phosphorylate several ion channels and may regulate their activity in cancer, including the amiloride-sensitive epithelial sodium channel (ENaC), transient receptor potential canonical channel 6 (TRPC6) and chloride channel 3 (ClC3)." (PMID 36123332, 2022). "TRPC6 (encoded by the gene TRPC6) is a receptor-activated nonselective cation channel that plays an oncogenic role by inducing cation influx and intracellular Ca2+ signaling in cancer cells." (PMID 36123332, 2022). "TRPC6 may be overexpressed in cancers due to activating the TRPC6-NFAT pathway." (PMID 36045706, 2021). "There are now multiple in vitro studies that have reported that inhibition or genetic knock-down of TRPC6 significantly reduces cancer cell migration and proliferation, suggesting that TRPC6 inhibition may be beneficial both in terms of cardioprotection from doxorubicin and anti-tumor efficacy." (PMID 34575190, 2021). "Indeed, while TRPC6 activation is known to promote cell proliferation, its overactivation by hyperforin was reported to induce a significant disorder in Ca2+ signaling that affects cell proliferation and induces apoptosis in cancer cells." (PMID 33916304, 2021). "Therefore, it should be an interesting topic to investigate why the expression of TRPC6 is cell cycle-dependent and whether such dependence is unique in cancer cells." (PMID 28030826, 2017). "Therefore, investigation of the role of fibronectin and ZO-1 in mediating TRPC6 regulation of cancer cell invasion may serve as an interesting topic for our future studies." (PMID 28030826, 2017). "Studies have shown that the overexpression of TRPC6 and TRPM7 correlates with more aggressive cancer phenotypes, as they help cancer cells adapt to the stressful tumor microenvironment by maintaining calcium homeostasis." (PMID 39768254, 2024). "We evaluated the distribution of the TRP family in C1–C6 pan-cancer immune subtypes and observed that TRPC4, TRPC6, TRPM4, TRPV2, TRPV4, MCOLN1, and PKD2L1 had the potential to predict the immune subtype." (PMID 36830651, 2023). "In kidney cancer, WNK1 is found to activate TRPC6-induced Ca2+-NFAT signaling, which promotes the proliferation and migration of cancer cells." (PMID 36123332, 2022). "Based on their previously well-known role in cancer and metastasis, the presence of the four ion channels (HERG/Kv11.1, TRPC1, TRPC6, and TRPV6) were screened in (BNL and 1MEA) cells using a high throughput 96-well in-cell western assay (ICW)." (PMID 31627357, 2019). "TRPV1, TRPC1, TRPC6, and TRPM5 are also increased in cancer tissues, but further experiments are required to study the underlying mechanisms." (PMID 27023518, 2016).
cancer (continued). "In particular, TRPC1 and TRPC6 have been involved in SOCE-mediated proliferation and cytokinesis in a number of cancer types." (PMID 25126575, 2014). "As both other TRPC subgroup members TRPC3 and TRPC6, TRPC7 is suggested to play a potential role in the physiology and pathology of neurological disorders, in the cardiovascular system, and in cancer cell growth and progression." (PMID 34828338, 2021). "The role of TRPC6 in cancer growth and development is not clear; however multiple mechanisms are involved in TRPC6 channel activation and regulation in cancer cells." (PMID 23976973, 2013). "Our results confirm that TRPC6 is not present in the normal breast tissue, while it is present in the cancer tissues (n = 5 for each sample)." (PMID 19689790, 2009). "TRPC6 expression was absent in cancer cells in 7/10 patient samples (Figure 2adii)." (PMID 31288452, 2019). "No data are available on the expression of TRPC6 in human carcinoma tissue." (PMID 18452628, 2008). "SKF-96365, a non-specific TRPC6 and TRPC7 antagonist, displays cytotoxic effects in several cancer cell types." (PMID 34458247, 2021).